LGI1 (leucine rich glioma inactivated 1)
Diseases named in the same sentence as LGI1 in open-access papers (continued):
Sharing a sentence is not in itself a finding about the gene and the disease.
epilepsy (continued). "A study using a series of LGI1 and ADAM22 hypomorphic mice revealed that ~50 % of LGI1 and ~10 % of ADAM22 protein levels are sufficient to prevent lethal epilepsy." (PMID 39984135, 2025). "The expression levels of mGluR1α, LGI1, and EAAT1 in the amygdala of the patients with epilepsy duration of >30 years were significantly lower than in subjects with a duration of <30 years (P ≤ 0.05)." (PMID 37658249, 2024). "Therefore the low prevalence of ADPEAF may understate the importance of LGI1 as an epilepsy gene." (PMID 23713523, 2013). "LGI2 should be considered a candidate gene for common remitting childhood epilepsies, and LGI2-to-LGI1 transition for mechanisms of childhood epilepsy remission." (PMID 21829378, 2011). "Hence, we suggest that there is a similar underlying disease mechanism for LGI1 and LGI2 and we propose that each of the LGI family members might be responsible for phenotypically similar, mechanistically related but genotypically distinct forms of epilepsy." (PMID 20863412, 2010). "LGI2 acts at least in part through the same ADAM receptors as LGI1, but earlier, ensuring electrical stability (absence of epilepsy) during pruning years, preceding this same function performed by LGI1 in later years." (PMID 21829378, 2011). "After symptom control, immunotherapies could be discontinued without early deteriorations, regardless of titers (NMDAR-6, LGI1-1, -3, -5, -7 [epilepsy persisted], -8, -9, 10, CASPR2-1, -4 [epilepsy persisted],-5, -6; two of these patients relapsed after > 1 year: NMDAR-6; LGI1-9)." (PMID 33025119, 2021). "In striking contrast, the reexpression of Lgi1R474Q transgene (Lgi1–/–;R474Q) could not rescue the epileptic phenotype of the Lgi1–/– mouse, showing the premature death due to lethal epilepsy." (PMID 29670100, 2018). "The LGI1/ADAM23 (ligand-receptor) complex is considered “an exciting therapeutic target for human epilepsy” and the same can be stated about BRUNOL4, since alterations in this gene are involved not only in epilepsy but also in other neurological conditions, such as autism." (PMID 24278214, 2013). "However, LGI3 does not rescue the LGI1 knockout mouse epilepsy, and therefore the two proteins are at least not interchangeable." (PMID 21829378, 2011). "LGI2 is a paralog of LGI1 which is the causal gene for ADTLE/ADPEAF (autosomal-dominant temporal lobe epilepsy/autosomal dominant partial epilepsy with auditory features, MIM# 600512), a non-remitting epilepsy in humans with onset typically in adolescence or early adulthood." (PMID 26084559, 2015). "As epileptiform activity is observed in animals treated with LGI1-Abs, there are also good reasons to believe that the lack of LTP observed in these animals is in fact due to the epilepsy-induced occlusion of LTP." (PMID 36078121, 2022).
Hyponatremia (65 papers, 2016 to 2026). An abnormally decreased sodium concentration in the blood. "Regarding diagnostic findings, hyponatremia (4/26, 15% vs 22/30, 73%; p < 0.001) and LGI1-Abs in the CSF (12/25, 48% vs 23/29, 79%; p = 0.039) were significantly less frequent during the relapse." (PMID 38603771, 2024). "We present a patient with dystonic seizures, progressive cognitive decline, psychiatric symptoms and short-term memory loss, and mild hyponatremia diagnosed with anti-LGI-1 antibody limbic encephalitis." (PMID 34437034, 2021). "The pathogenic mechanism involved in the onset of hyponatremia is likely associated with lowered antidiuretic hormone levels due to the effects of LGI1 antibodies on the hypothalamic paraventricular nucleus and kidney." (PMID 29980179, 2018). "Hyponatremia, defined as a serum sodium concentration of less than 135 mEq/L, which is frequently observed in LE associated with anti-LGI1 antibodies, was observed in 6 (43%) patients at admission." (PMID 28272206, 2017). "LGI1-Ab was reported to associate with seizures, amnesia, confusion, hyponatraemia and a good prognosis, while CASPR2-Ab with peripheral presentations, probable risk for tumor and a poor prognosis." (PMID 26983964, 2016). "Lgi1 antibodies are also associated with hyponatremia secondary to SIADH due to their binding to hypothalamic paraventricular nucleus neurons." (PMID 27247812, 2016). "The mechanisms behind the hyponatremia in LGI1-AE is speculated to be caused by hypothalamic neuronal impairment or LGI1 channel dysregulation in the renal epithelium." (PMID 34975832, 2021). "Autoimmune limbic encephalitis (LE) with leucine-rich glioma-inactivated 1 (LGI1) antibodies is rare but treatable, often presenting as rapidly progressive cognitive decline, behavioural changes, and hyponatraemia." (PMID 41982561, 2026). "Anti-LGI1 AE is characterized by rapid progressive dementia, sleep disorders, refractory hyponatremia, and fascio-brachial dystonic seizures." (PMID 39820999, 2025). "Investigation revealed hyponatremia, bilateral mesial temporal lobe high signal abnormality worse on the right on MRI and CSF positive anti-LGI1 antibodies (1:30)." (PMID 39734683, 2024). "Recent studies have shown that up to 87% of patients with anti-LGI1 LE will develop hyponatremia over the course of the disease." (PMID 39006729, 2024). "Only 4 patients had FBDS and 3 patients had hyponatremia which are commonly encountered in adult LGI1-IgG-positive patients." (PMID 37391712, 2023). "The incidence of hyponatremia in the present study was also within the scope of previous studies (66.7 vs. 39–80%, respectively); hyponatremia is often caused by inappropriate secretion of the antidiuretic hormone, which may be related to the expression of LGI1 in the hypothalamus and the kidney." (PMID 34168612, 2021). "Hyponatraemia (5/6) and faciobrachial dystonic seizures (3/6) were the most frequent in the LGI1 patient group." (PMID 33767656, 2021). "LGI1-AE is characterized by confusion, cognitive impairment, sleep disorder, refractory hyponatremia, fascio-brachial dystonic seizures and high signal in medial temporal lobe and hippocampus." (PMID 34836497, 2021). "LGI1-AE patients with abnormal CSF findings and with hyponatremia had the highest CSF-NfL concentrations." (PMID 34975832, 2021). "Emergency physicians encountering the additional findings of faciobrachial dystonic seizures, hyponatremia, and MRI abnormalities in the limbic region should have high clinical suspicion for anti-LGI-1 antibody limbic encephalitis." (PMID 34437034, 2021). "In LGI1-AE, CSF-NfL levels were higher in patients with an abnormal CSF (p=0.003) and hyponatremia (p=0.005)." (PMID 34975832, 2021). "Regarding the laboratory findings, 20/33 (60.6%) patients had hyponatremia (serum Na+<134 mmol/L); the positive rates of LGI1 antibody in blood and CSF were 100% and 93.5%, respectively; and 27/29 (93.1%) patients were LGI1‐positive in both the blood and CSF." (PMID 34291554, 2021).
Hyponatremia (continued). "Laboratory test included serum hyponatremia, positive serum LGI1 and GABABR1 antibodies using transfected cell-based assays." (PMID 34836497, 2021). "Limbic encephalitis (LE) with antibodies against leucine-rich glioma inactivated protein 1 (LGI1) is an autoimmune disease with variable clinical features, including seizures, cognitive disorders, psychiatric disturbances, and hyponatremia." (PMID 32153488, 2020). "Hyponatremia, a commonly described symptom resulting from effects of anti‐LGI1 antibodies on hypothalamus and kidneys, was present in 56.3% of our patients, in line with previous studies." (PMID 32783406, 2020). "For example, seizures and hyponatremia were more common in anti-LGI1-IgG positive patients while neuropathic pain was more common in anti-CASPR2-IgG positive patients." (PMID 31178819, 2019). "Herein, we reported a 56-year-old man presenting as rapidly progressive dementia and hyponatremia with anti-LGI1 AE, and described the clinical manifestations, imaging findings of ASL, and treatment and outcomes." (PMID 30732585, 2019). "Over half of patients suffering from LGI1 antibody encephalitis also exhibit hyponatremia and in most cases, refractory hyponatremia." (PMID 29980179, 2018). "Patients with LGI1 antibodies typically develop limbic encephalitis and suffer from amnesia, confusion, personality change or psychosis, seizures, and often hyponatremia." (PMID 29093718, 2017). "Hyponatremia, a hallmark of anti-LGI1 LE observed in 56.3% of cases, was absent in this patient despite repeated blood tests." (PMID 40007925, 2025). "The case also highlights the varied and nonspecific symptoms associated with anti-LGI1 LE, including faciobrachial dystonic seizures, hyponatremia, sleep disturbances, and various cognitive and psychiatric dysfunctions." (PMID 39006729, 2024). "Hyponatremia is observed in up to 60% of anti-LGI1 patients." (PMID 37278857, 2024). "Moreover, anti-LGI1 AE patients are prone to skin reactions and hyponatremia with CBZ and OXC or drug side effects such as adverse psychiatric reactions, memory loss, and tremor with VPA and LEV." (PMID 37034075, 2023). "Herein, we describe a 48 years old man presenting with rapidly progressive cognitive decline and hyponatremia diagnosed with anti LGI1 AE, occurring shortly after the second dose of mRNA COVID -19 vaccine and possibly representing a severe adverse event related to the vaccination." (PMID 35069602, 2022). "Notably, the refractory hyponatremia is a characteristic feature of anti-LGI1 AE, and 60%~ 88% of the patients with anti-LGI1 antibodies may develop hyponatremia during the course of the disease." (PMID 39820999, 2025). "Sodium channel blockers may be preferred for treating seizures in anti-LGI1 AE, but anti-LGI1 AE patients are prone to skin reactions and hyponatremia with CBZ and OXC or drug side effects such as adverse psychiatric reactions, memory loss, and tremor with VPA and LEV." (PMID 37034075, 2023). "Additionally, hyponatremia was found in serum analyses in both cases with anti-LGI-1 LE." (PMID 32486044, 2020). "In addition, hyponatremia, a characteristic manifestation of anti-LGI1 AE, is considered to be a prodromal symptom and may be related to the syndrome of inappropriate secretion of antidiuretic hormone caused by simultaneous expression of LGI1 in the hypothalamus and kidneys." (PMID 40519939, 2025). "Seizures, cognitive impairments, hyponatremia, and abnormal brain MRI T2/FLAIR signals are among the mostly observed clinical manifestations in patients with anti-LGI1 AE." (PMID 40217477, 2023). "Hyponatremia was present in three patients, one with anti-AMPAR and in both with anti-LGI1, and improved after immunotherapy." (PMID 31139134, 2019). "Anti-LGI1 LE is characterized by symptoms including neuropsychiatric disturbances, memory deterioration, epileptic seizures, sleep changes, FBDS, dysautonomia, and hyponatremia." (PMID 39664290, 2024).
Hyponatremia (continued). "Anti-LGI1 AE is characterized by cognitive impairment or rapid progressive dementia, psychiatric disorders, faciobrachial dystonic seizures (FBDS) and refractory hyponatremia." (PMID 30732585, 2019). "The leucine-rich glioma-inactivated protein 1 (LGI1) antibody-related autoimmune encephalitis can occur alone or in the setting of a malignancy and manifest with faciobrachial dystonic seizures (FBDS), cognitive decline, hyponatremia, and neuropsychiatric disorders." (PMID 39734683, 2024). "Anti-LGI1 AE is a heterogeneous condition, as patients typically experience limbic symptoms such as rapidly declining memory and neuropsychiatric/behavioral problems; faciobrachial dystonic seizures (FBDS) or other types of seizure; and metabolic derangements such as hyponatremia." (PMID 40217477, 2023). "For example, the presence of faciobrachial dystonic seizures (FBDS) and hyponatraemia strongly suggest LGI1-reactivity, whereas the presence of neuromyotonia or other features of Morvan's syndrome suggest CASPR2-directed autoantibodies (sometimes accompanied by LGI1-antibodies)." (PMID 27450643, 2016).
Cognitive impairment (62 papers, 2014 to 2026). Abnormal cognition is characterized by deficits in thinking, reasoning, or remembering. "Limbic encephalitis with leucine-rich glioma inactivated 1 (LGI1) protein autoantibodies is associated with cognitive impairment, psychiatric symptoms, and seizures, including faciobrachial dystonic seizures (FBDS)." (PMID 39984135, 2025). "At the clinical level, anti-NMDAR, LGI1 and mGluR5 autoantibodies were strongly associated with cognitive impairment, AD-like phenotypes and profound amnesia, respectively." (PMID 40537813, 2025). "Studies have shown that cognitive impairment in patients with anti-LGI1 AE may be caused by structural damage to the hippocampal memory system." (PMID 40519939, 2025). "These cases underscore the difficulty associated with diagnosing LGI1 LE and confirm earlier findings that cognitive deficits may persist months to years after treatment." (PMID 26881156, 2016). "In these patients, subacute onset, rapid evolution of symptoms, early severe cognitive impairment, and seizures represent red flags for neurodegenerative disorders and should prompt alternative diagnoses such as LGI1-Ab AE." (PMID 40274643, 2025). "Cognitive impairment, as one of the common neurological disorders in anti-LGI1 AE, increases the difficulty of differential diagnosis from neurodegenerative diseases." (PMID 40519939, 2025). "In all seven studies involving patients with anti-LGI1, cognitive impairment was observed in all patients, as shown by the Montreal Cognitive Assessment (MoCA) scores." (PMID 38322089, 2024). "In a systematic review that involved 485 subjects, 412 people with anti-LGI1 had cognitive impairment." (PMID 38322089, 2024). "This provides a potential molecular mechanism for cognitive impairment seen in patients with anti-LGI1 AE." (PMID 40217477, 2023). "Seizures occurred in the 12 GABAbR-positive patients; eight patients with LGI1 antibodies presented with seizures or cognitive impairment, which was in line with previously reported studies." (PMID 35720290, 2022). "In LGI1-antibody encephalitis, ~80% of patients noticed that faciobrachial dystonic seizures typically precede onset of marked cognitive impairment." (PMID 34108243, 2021). "The two cardinal clinical features of LGI1-antibody encephalitis are seizures and cognitive impairment." (PMID 31655889, 2021). "FBDS often precede the development of the cognitive impairment seen in patients with LGI1 antibodies which predominantly involves episodic memory and executive function." (PMID 31655889, 2021). "Anti-leucine-rich glioma-inactivated 1 limbic encephalitis (LGI1-LE) is an auto-antibody mediated disorder characterized by an acute to sub-acute onset of confusion and cognitive impairment, facio-brachial dystonic seizures (FBDS) and psychiatric disturbances." (PMID 32894089, 2020). "The FCA detected higher overall LGI1-IgG levels in patients with cognitive impairment (P = 0.01, Mann-Whitney U-test)." (PMID 29272336, 2018). "Patients with FBDS alone almost exclusively had LGI1-IgG4 antibodies (P = 0.009, Mann-Whitney U-test) whereas, overall, patients with cognitive impairment showed higher proportions of LGI1-IgG1 antibodies (P = 0.03, Mann-Whitney U-test)." (PMID 29272336, 2018). "Subsequently, patients often developed cognitive impairment accompanied by an increase in both LGI1-IgG levels and frequency of FBDS." (PMID 29272336, 2018). "This agrees with the different clinical features of CASPR2-Ab and LGI1-Ab that CASPR2-Ab was in association with PNH and Morvan syndrome while LGI1-Ab with memory loss, cognitive impairment and seizures." (PMID 26983964, 2016). "Patients with anti-LGI1 syndrome presented with symptoms of a classic limbic encephalitis including cognitive deficits and focal seizures." (PMID 24950993, 2014).
Cognitive impairment (continued). "The animal models introduced here provide valuable insights into the evolution of limbic encephalitis with antibodies to LGI1 and can eventually help to understand the persisting and secondary synaptic changes that lead to progressive cognitive impairment and chronic epilepsy in some patients." (PMID 39984135, 2025). "The finding of complement deposition suggests that LGI1-Abs can induce neuronal death through the activation of the complement cascade which may explain the persistence of long-term cognitive deficits as well as structural brain changes in affected patients." (PMID 36979644, 2023). "A recent study reported persisting long-term cognitive impairment in LGI1-AE, but whether these are temporarily progressing is unknown." (PMID 34975832, 2021). "Although cognitive impairment, seizures and behavioral abnormalities typically dominate the clinical picture, some LGI1-Ab patients develop parkinsonism (2–6%) or involuntary movements (2–12%) such as chorea or myoclonus, which may raise the suspicion of a neurodegenerative disorder." (PMID 40274643, 2025). "Patients with LGI1-IgG often present with acute behavioral changes, psychosis, seizures, faciobrachial dystonic seizures (FBDS), and cognitive impairment." (PMID 40703404, 2025). "In a study pooling LGI1- and CASPR2-Ab positive cases, some form of cognitive impairment was detected in 28% of patients, with 9% showing a severe dementia at last follow-up using the clinical dementia rating scale (CDR ≥ 0.5)." (PMID 36979644, 2023). "Eighteen months after the onset of symptoms, the patient did not experience seizures, cognitive impairment, or excessive sweating and tested negative for both anti-LGI1 and anti-MOG antibodies." (PMID 40703404, 2025). "The most common clinical manifestations of AE were seizures, cognitive impairment, decreased level of consciousness and psychosis in our cohort, and the most common antibody types in AE patients were anti-NMDAR and LGI1, which are consistent with previous studies." (PMID 37503335, 2023). "We compare those with and without cognitive impairment, quantify the relative effects of AEDs and immunotherapy, address the hypothesis that early immunotherapy administration may prevent progression to cognitive impairment, and explore potential pathogenic mechanisms of the LGI1 antibodies." (PMID 29272336, 2018). "The one patient in our study who had LGI1-AE without cognitive impairment, had the lowest CSF-NfL concentration at diagnosis, speculating that lower CSF-NfL levels might reflect lower neurodegeneration and thus no cognitive decline." (PMID 34975832, 2021). "Furthermore, LGI1-IgG1 antibodies were undetectable in 7/8 (88%) patients without cognitive impairment versus 14/41 (34%) with cognitive impairment (P = 0.01, Fisher’s), and greater LGI1-IgG1 proportions correlated modestly with poorer cognitive scores (P = 0.01 and 0.04)." (PMID 29272336, 2018).